CHRNA3 (cholinergic receptor nicotinic alpha 3 subunit)
Diseases named in the same sentence as CHRNA3 in open-access papers (continued):
Sharing a sentence is not in itself a finding about the gene and the disease.
nicotine dependence (continued). "We observed significant associations of rs8034191 and rs1051730 in the CHRNA3/5 locus with FTND score, but we found differential evidence for association of SNPs related to nicotine dependence with emphysema severity according to current smoking status." (PMID 21232152, 2011). "With the current sample (TI ≤ 40, n = 76; TI > 40, n = 47; Controls, n = 29; COPD, n = 94), the minimal detectable absolute differences to achieve 80% power were ~25 percentage points for CHRNA3–nicotine dependence contrasts and ~11 percentage points for EPHX1–COPD." (PMID 41301874, 2025). "CHRNB3 is a kind of nicotinic acetylcholine receptor, and a study among Caucasian smokers involving 661 lung ADC cases and 1347 controls found that two CHRNA3 SNPs (rs1051730 and rs12914385) associated with ADC risk had significant indirect effects on lung ADC risk through nicotine dependence." (PMID 35499292, 2022). "The CHRNA3/CHRNA5/CHRNB4 gene cluster, encoding for the α3, α5 and β4 nicotinic acetylcholine receptor (nAChR) subunits, has drawn interest due to its implication in nicotine dependence and lung cancer." (PMID 34206324, 2021). "In addition, several other COPD GWAS loci have strong candidate genes, such as the nicotinic acetylcholine receptor genes that have been related to nicotine addiction (CHRNA3 and CHRNA5) and TGFB2 (part of the TGFBeta pathway)." (PMID 30262855, 2018). "We previously undertook pooled sequencing of the coding regions and flanking sequence of the CHRNA5, CHRNA3, CHRNB4, CHRNA6 and CHRNB3 genes and found that rare missense variants at conserved residues in CHRNB4 are associated with reduced risk of nicotine dependence among African Americans." (PMID 24804708, 2014). "The subjects in recent studies are former or current smokers, and as such it is difficult to identify whether variants in the CHRNA3/5 locus have a direct influence on COPD independent of smoking behavior or nicotine dependence." (PMID 25051068, 2014). "Previously, we had reported other SNPs in smoking-related genes as NRXN1, DRD4, HTR2A, CHRNA3, CHRNA5, and CYP2A6 in Mexican mestizo, focused on smokers enrolled in a smoking cessation program, mostly with high tobacco consumption and nicotine dependence." (PMID 34205269, 2021). "There are differences in the genotype frequencies of SNPs in genes related to nicotine metabolism (CYP2A6) and nicotine dependence (NRXN1, DRD4, CHRNA3-CHRNA5)." (PMID 34205269, 2021). "Both the CHRNA3 and CHRNA5 genes are expressed in human brain regions relevant to nicotine addiction, such as the nucleus accumbens, amygdala, and entorhinal cortex." (PMID 31362771, 2019). "Second, the neurotransmitter receptors in this pathway (including CHRNA5, CHRNA3, CHRNB4, and CHRND) participate in the biological process by which smoking induces nicotine dependence." (PMID 30104567, 2018). "Nine SNPs in CHRNA3 had significant total and direct effects; seven of these had significant indirect effects on lung ADC through nicotine dependence." (PMID 25233467, 2014). "The CHRNA5 rs16969968, the CHRNA3 rs578776, CHRNA3 rs1051730, and the LOC123688 rs8034191 have all been found to be related to smoking rate and other measures of nicotine dependence." (PMID 24065931, 2013). "The CHRNA3 and CHRNA5 genes participate in the mechanism of nicotine addiction and lung damage." (PMID 33801584, 2021). "While SNPs in CHRNA3/5 were associated with nicotine dependence measured with FTND, surprisingly, nicotine dependence was a negative predictor for emphysema on CT in COPD patients and even in control smokers." (PMID 21232152, 2011). "However, none of the baseline measures of nicotine dependence, depressed mood, or trait affective disposition differed by CHRNA3 rs578776 genotype in the present study." (PMID 24065931, 2013).
chronic obstructive pulmonary disease (14 papers, 2011 to 2025). A chronic and progressive lung disorder characterized by the loss of elasticity of the bronchial tree and the air sacs, destruction of the air sacs wall, thickening of the bronchial wall, and mucous accumulation in the bronchial tree. "In CHRNA3 (encoding cholinergic receptor nicotinic α-3), rs55958997 demonstrated associations with chronic obstructive pulmonary disease and ventilator dependence." (PMID 32981348, 2020). "Several single nucleotide polymorphisms (SNPs) in an α-neuronal nicotinic acetylcholine receptor subunit (CHRNA3/5) were identified to be associated with chronic obstructive pulmonary disease (COPD) in a study based on a Norwegian population." (PMID 25051068, 2014). "Nearby genes of interest include CHRNA3 and CHRNA5; variants in this locus are associated with chronic obstructive pulmonary disease and lung cancer." (PMID 35173190, 2022).
schizophrenia (9 papers, 2016 to 2022). A major psychotic disorder characterized by abnormalities in the perception or expression of reality. "The CHRNA3-CHRNA5-CHRNB4 gene cluster is strongly associated with schizophrenia; it consists of genes in high LD with each other and has been linked to nicotine dependence." (PMID 28963561, 2017). "The CHRNA3/5 SNP (rs951266) mainly impacts lifespan through smoking and schizophrenia predisposition; the SNX29 SNP rs729583 seems to have little impact on most of the 11 traits; the FTO SNP rs9939973 essentially exerts its effect on BMI and its downstream traits." (PMID 28748955, 2017). "TCF4 binding sites were also found at other schizophrenia risk loci including the nicotinic acetylcholine receptor cluster, CHRNA5/CHRNA3/CHRNB4 and SETD1A." (PMID 29228394, 2018). "Furthermore, GWAS found that the risk of schizophrenia was associated with a cluster of genes (CHRNA5, CHRNA3 and CHRNB5) on chromosome 15, which was also suggested to be associated with both early age at onset of cigarette smoking and heavy cigarette smoking." (PMID 32107650, 2020). "In particular, the difference in the rules of allele interactions between patients with schizophrenia and controls was revealed when the effects exerted on PPI by polymorphism rs4680 in the COMT gene, as well as polymorphisms rs1051730 and rs1317286 in the CHRNA3 gene, were estimated." (PMID 35846783, 2022).
neuroblastoma (7 papers, 2011 to 2024). Neuroblastoma (NB) is the most common solid, extracranial childhood tumor. "MRD detection in BM samples evaluated by a set of five markers (CHRNA3, DDC, GAP43, PHOX2B, and TH) was associated with poor outcome in patients aged over 1 year with stage 4 neuroblastoma." (PMID 31214500, 2019). "When BM samples are evaluated by a set of five markers (CHRNA3, DDC, GAP43, PHOX2B, and TH), unfavorable outcome in localized neuroblastoma patients is associated with the detection of more than one positive-marker." (PMID 31214500, 2019). "We confirmed that the commonly used neuroblastoma MRD markers (including PHOX2B, TH, CHRNA3, GAP43) are rarely expressed in mesenchymal neuroblastoma cell lines." (PMID 39722049, 2024). "The presence of neuroblastoma-specific mRNA in the cellular compartment of blood and bone marrow, such as PHOX2B, TH and CHRNA3, has been shown to correlate with outcome, enabling response monitoring in patients with high-risk disease." (PMID 37046768, 2023). "The mRNA content was determined using several multiplex droplet digital PCR (ddPCR) assays for a neuroblastoma-specific gene panel (PHOX2B, TH, CHRNA3) and a cell cycle regulation panel (E2F1, CDC6, ATAD2, H2AFZ, MCM2, DHFR)." (PMID 37046768, 2023). "To study cfRNA in limited volume samples of pediatric patients with neuroblastoma, we first designed and optimized a multiplex ddPCR which included the neuroblastoma-specific targets PHOX2B, CHRNA3 and TH, and GUSB as a reference gene." (PMID 37046768, 2023). "When compared with the neuroblastoma genes, 7/14 DHFR-positive patients were also positive for PHOX2B and/or CHRNA3." (PMID 37046768, 2023). "Further, different mRNA markers are being explored for MRD detection in blood (PHOX2B, TH, DDC, DBH, and CHRNA3) and bone marrow (PHOX2B, TH, DDC, CHRNA3, and GAP43) from neuroblastoma patients." (PMID 31897843, 2020).
lung adenocarcinoma (4 papers, 2014 to 2019). A carcinoma that arises from the lung and is characterized by the presence of malignant glandular epithelial cells. "The top two CHRNA3 SNPs associated with the risk for lung adenocarcinoma were rs1051730 and rs12914385 (p-value = 1.9×10−10 and 1.1×10−10, respectively)." (PMID 25233467, 2014).
depression (3 papers, 2017 to 2021). "Downregulation of cholinergic signaling in the habenula, including decreased expression of the genes related to cholinergic signaling, such as ChAT, CHT, VAChT, CHRNA3, and CHRNB4, has been demonstrated in an animal model of depression and in suicide victims diagnosed with major depressive disorder." (PMID 30873055, 2019). "Here, we demonstrated that the expression levels of cholinergic signaling genes (CHAT, VACHT, CHT, CHRNA3, CHRNB3 and CHRNB4) were down-regulated in a chronic restraint stress (CRS) rat model of depression, in which rats display depression-like behaviors such as anhedonia and mood despair." (PMID 28420875, 2017).
emphysema (3 papers, 2011 to 2022). "Previously reported associations of these genetic variants include: airflow limitation (CHRNA3/5, IREB2, HHIP), emphysema susceptibility and severity (CHRNA3/5, BICD1), chronic bronchitis phenotype, exacerbation rate (HHIP) and pulmonary hypertension pathogenesis." (PMID 35330379, 2022). "An association of genetic variants in CHRNA3/5 with severity of emphysema was only found in former smokers, but not in current smokers." (PMID 21232152, 2011). "An association of genetic variants in CHRNA3/5 (rs8034191 and rs1051730) with severity of emphysema was found in former smokers, but not in current smokers." (PMID 21232152, 2011). "In the full group of currently smoking subjects, the A-allele of rs1051730 was associated with increased FTND score, while neither SNP in the CHRNA3/5 region (rs8034191 and rs1051730) was associated with FEV1 (% predicted), affection status of COPD, nor percent of emphysema." (PMID 21232152, 2011).
lumbar disc herniation (3 papers, 2019 to 2025). "A case in point is the rs8040868 CT genotype of the CHRNA3 gene, which has been shown to be significantly correlated with the risk of lumbar disc herniation in the male population." (PMID 40709036, 2025). "Our data suggest that gene variance in the CHRNA5/CHRNA3 is associated with risk of lumbar disc herniation in the case-control study." (PMID 31362771, 2019). "This study’s aim is to test whether single-nucleotide polymorphisms in the CHRNA5/CHRNA3 gene are associated with lumbar disc herniation risk." (PMID 31362771, 2019).
lung diseases (3 papers, 2012 to 2015). "IREB2 is located in the region near the CHRNA3/CHRNA5/CHRNAB4 genes cluster with a possible role of lung diseases development." (PMID 26310313, 2015). "Because CHRNA3 is also a receptor of NNK, we could assume that NNK modulates the adverse genetic effect of rs6495309C genotypes on increasing lung diseases risk because NNK can cause gene mutation, DNA damage, activation of oncogenes and tumor-related signal pathways." (PMID 23056235, 2012).
gastric cancer (2 papers, 2015 to 2016). A primary or metastatic malignant neoplasm involving the stomach. "RASSF1A, p14ARF, and MGMT; CHRNA3, DOK1, and GNMT; p16, hMLH1, MINT1, MINT2, MINT12, MINT25, and MINT31; APC, CDH1, MHL1, CDKN2A, CDKN2B, and RUNX3; CDH1; DKK3; PTEN; MGMT; TFPI2; CACNA2D3; PCDH10; SOX2; MAL; and COX2 were previously reported to be hypermethylated in gastric cancer." (PMID 26121593, 2015).
Hypertension (2 papers, 2015 to 2020). The presence of chronic increased pressure in the systemic arterial system. "Our study with stratification of testosterone levels has enhanced the association of variants of molecules in the EPHB6 signaling pathway with hypertension risks and revealed the association of a CHRNA3 variant with hypertension risks." (PMID 33329690, 2020). "We used 750 hypogonadic men with hypertension as cases and 750 age-matched normotensive hypogonadic men as controls to assess the association of CHRNA3 variants with hypertension." (PMID 33329690, 2020). "The result revealed that SNV rs3743076 in the fourth intron of CHRNA3 was significantly associated with hypertension risks in the hypogonadic males." (PMID 33329690, 2020). "This prompted us to conduct a human genetic study to assess the association of variants of a major nAChR subunit CHRNA3 with hypertension risks in hypogonadic male hypertensive patients." (PMID 33329690, 2020). "We conducted a human genetic study to assess the association of CHRNA3 variants with hypertension risks in hypogonadic males." (PMID 33329690, 2020). "In this study, we conducted a human genetic study to assess the association of variants in CHRNA3, the major subunit of nAChR in AGCCs, with hypertension risks in hypogonadic, hypertensive patients." (PMID 33329690, 2020). "In sum, the findings of our study indicate that the CHRNA3 rs6495308 genotype is an effect modifier of the association between daily cigarette consumption and hypertension in Chinese male smokers." (PMID 25874685, 2015). "Effects of the interaction between smoking quantity and CHRNA3 rs6495308 polymorphism on hypertension." (PMID 25874685, 2015). "Heavy smokers with the homozygous mutant CHRNA3 rs6495308 genotype exhibited a significantly greater risk of hypertension than light smokers with wild-type CHRNA3 rs6495308 genotypes." (PMID 25874685, 2015). "Indeed, SNV rs3743706 within CHRNA3 was found to be significantly associated with hypertension risks in this cohort." (PMID 33329690, 2020). "Consistent with this hypothesis, we demonstrated that hypogonadic patients with deleterious CHRNA3 variants had increased hypertension risks according to our human genetic study." (PMID 33329690, 2020). "After adjusting for marital status, family income, family history of hypertension, physical exercise and age at smoking initiation, heavy smokers with the homozygous mutant TT genotype of CHRNA3 rs6495308 were found to have the highest risk of hypertension (OR = 2.44, 95% CI = 1.27–4.68)." (PMID 25874685, 2015). "The purpose of this study is to determine whether the CHRNA3 rs6495308 genotype affects the association between daily cigarette consumption and hypertension." (PMID 25874685, 2015). "To fill this gap in the research, we focus in the current study on the effects on hypertension of the relationship between rs6495308 genotypes of the CHRNA3 gene and daily cigarette consumption." (PMID 25874685, 2015). "The results of the current study show that the interaction between daily cigarette consumption and the CHRNA3 rs6495308 genotype significantly affects hypertension." (PMID 25874685, 2015). "The positive interaction between heavy smoking and the homozygous mutant CHRNA3 rs6495308 genotype was found to affect the likelihood of hypertension in Chinese male smokers." (PMID 25874685, 2015). "After adjusting for age, education level, occupation, a family history of hypertension, physical exercise, age at smoking initiation and BMI, we found the interaction term between daily cigarette consumption and CHRNA3 rs6495308 genotype to be statistically significant (p < 0.05)." (PMID 25874685, 2015). "We also observed that the interaction between daily cigarette consumption and the CHRNA3 rs6495308 genotype may affect hypertension." (PMID 25874685, 2015).
Hypertension (continued). "Such individuals may have changed their lifestyles after being diagnosed with hypertension, and their use of antihypertensive medication may affect the measurement of blood pressure and the relationships between smoking quantity, CHRNA3 genotype variation and hypertension." (PMID 25874685, 2015). "However, the interaction between daily cigarette consumption and the CHRNA3 genotype may affect hypertension, as heavy smokers with the homozygous mutant genotype of CHRNA3 rs6495308 exhibited the highest risk of hypertension relative to the reference group." (PMID 25874685, 2015). "This prior knowledge plus our current findings from the human genetic study and mouse AGCC experiments allow us to propose the following model for the implication of the regulation of AGCC function by CHRNA3 and EPHB6 in human hypertension pathogenesis." (PMID 33329690, 2020).
alpha 1-antitrypsin deficiency (1 paper, 2012). Alpha-1-antitrypsin deficiency is a hereditary disease that develops in adulthood and is characterized by chronic liver disorders (cirrhosis), respiratory disorders (emphysema), and rarely panniculitis. "IREB2 and CHRNA3 are potential genetic modifiers of COPD phenotypes in individuals with severe AAT deficiency and may be sex-specific in their impact." (PMID 22356581, 2012).
Anxiety (1 paper, 2025). Intense feelings of nervousness, tension, or panic often arise in response to interpersonal stresses. "In particular, the activation of Chrna3 suppresses anxiety behavior." (PMID 40072069, 2025). "Thus, Chrna3 is deeply involved in the regulation of important neural functions such as anxiety, cognition, and reward, and it is becoming clear that changes in its expression level and activity are involved in the pathology of various psychiatric and neurological disorders." (PMID 40072069, 2025).
arterial diseases (1 paper, 2021). "This indicated that a tobacco-smoking-related gene (CHRNA3) and a thrombosis-related gene (F5) might play an essential role in PAD but not in other arterial diseases." (PMID 34943774, 2021).
autism (1 paper, 2018). Persistent deficits in social interaction and communication and interaction as well as a markedly restricted repertoire of activity and interest as well as repetitive patterns of behavior. "There was weak evidence for an association of the epigenetic score or genetic variation at CHRNA3 with ASD or any of the autism-related traits." (PMID 30498225, 2018).
cognitive decline (1 paper, 2025). "Microarray analysis of their hippocampi revealed that the cholinergic receptor nicotinic α3 subunit (Chrna3) was significantly reduced in mice with cognitive decline compared to controls." (PMID 40072069, 2025). "It was also demonstrated that reduced Chrna3 expression may be involved in cognitive decline among adult mice, and that nicotine and cytisine could inhibit this decline." (PMID 40072069, 2025). "We found that Chrna3 expression was significantly reduced in adult mice with cognitive decline compared to adult mice without cognitive decline." (PMID 40072069, 2025). "Although Chrna3 is not the most abundantly expressed nicotinic acetylcholine receptor (nAChR) subunit in the central nervous system, our results suggest that its expression was reduced in the hippocampus with cognitive decline." (PMID 40072069, 2025).
Cognitive impairment (1 paper, 2025). Abnormal cognition is characterized by deficits in thinking, reasoning, or remembering. "Despite cardiotoxic side effects preventing the approval of several α7nAChR agonists, nicotine-derived agonistic compounds like cytisine, which increase Chrna3 expression, appear promising for cognitive function and neurological disease-related cognitive impairment." (PMID 40072069, 2025).
colitis (1 paper, 2026). Inflammation of the colon. "Colitis significantly activated CHRNA3+ nociceptors via the NGF-TrkA/pERK/PIEZO2 pathway, converting them from mechanoinsensitive to mechanosensitive." (PMID 42157236, 2026).
colorectal cancer (1 paper, 2025). A primary or metastatic malignant neoplasm that affects the colon or rectum. "In colorectal cancer, high CHRNA3 expression was found to be associated with poor prognosis and to exhibit a strong physical interaction with CHRNA5." (PMID 41201200, 2025).